FAM163B (family with sequence similarity 163 member B)
Synonyms: C9orf166
Tractability: Antibody: UniProt predicts a signal peptide or a membrane-spanning region; the Human Protein Atlas places it where antibodies can reach.
Gene: Protein-coding gene on chromosome 9 (133,577,076 to 133,609,418, reverse strand). Ensembl gene ENSG00000196990.
Subcellular location: Membrane
Subcellular location (Human Protein Atlas): Cytosol; Nuclear bodies; Plasma membrane
Gene Ontology:
Molecular function: protein binding
Cellular component: membrane
Genetic constraint (gnomAD): Loss-of-function variants: 6 observed, 7.38 expected, observed/expected ratio (o/e) 0.81, 90% interval 0.44 to 1.57. That is too few expected variants to judge how well the gene tolerates losing a copy. Missense variants: 250 observed, 235.77 expected, observed/expected ratio (o/e) 1.06, 90% interval 0.96 to 1.18. Synonymous variants: 120 observed, 107.96 expected, observed/expected ratio (o/e) 1.11, 90% interval 0.96 to 1.29.
Homologues: Orthologues: chimpanzee FAM163B (99% identical), macaque FAM163B (99% identical), mouse Fam163b (90% identical), pig FAM163B (90% identical), guinea pig FAM163B (89% identical), dog FAM163B (89% identical), rat Fam163b (88% identical), tropical clawed frog fam163b (67% identical), zebrafish fam163ba (58% identical), zebrafish FAM163B (44% identical).
Diseases named in the same sentence as FAM163B in open-access papers:
FAM163B is named in the same sentence as 1 disease in open-access papers, as found by Europe PMC text mining. Sharing a sentence is not in itself a finding about the gene and the disease. The quoted sentences say what the papers report.
cancer (1 paper, 2023). A tumor composed of atypical neoplastic, often pleomorphic cells that invade other tissues. "The gene with the second highest MS was FAM163B, which has not yet been elucidated, but its paralog FAM163A (also known as NDSP) is associated with an increased risk for the development of cancer metastasis in bone marrow." (PMID 37761960, 2023).